ZNF175 (zinc finger protein 175)
Description:
Down-regulates the expression of several chemokine receptors. Interferes with HIV-1 replication by suppressing Tat-induced viral LTR promoter activity.
Synonyms: OTK18
Tractability: PROTAC: ubiquitination databases record sites on it.
Gene: Protein-coding gene on chromosome 19 (51,571,283 to 51,592,510, forward strand). Ensembl gene ENSG00000105497.
Subcellular location: Cytoplasm; Nucleus
Subcellular location (Human Protein Atlas): Nucleoli; Cytosol
Pathways (Reactome):
Gene expression (Transcription): Generic Transcription Pathway
Gene Ontology:
Molecular function: DNA-binding transcription activator activity, RNA polymerase II-specific; DNA-binding transcription repressor activity, RNA polymerase II-specific; protein binding; RNA polymerase II transcription regulatory region sequence-specific DNA binding; DNA-binding transcription factor activity; sequence-specific DNA binding
Biological process: negative regulation of transcription by RNA polymerase II; positive regulation of transcription by RNA polymerase II; regulation of DNA-templated transcription
Cellular component: cytosol; nucleolus; cytoplasm; nuclear lumen; nucleus
Genetic constraint (gnomAD): Loss-of-function variants: 8 observed, 14.96 expected, observed/expected ratio (o/e) 0.53, 90% interval 0.31 to 0.96. The synonymous counts are far from expectation, so gnomAD's model fits this gene poorly and the ratio says little. Missense variants: 764 observed, 894.09 expected, observed/expected ratio (o/e) 0.85, 90% interval 0.8 to 0.91. Synonymous variants: 255 observed, 315.27 expected, observed/expected ratio (o/e) 0.81, 90% interval 0.73 to 0.9.
Homologues: Orthologues: chimpanzee ZNF175 (98% identical), macaque ZNF175 (95% identical), pig ZNF175 (75% identical). Paralogues in human: ZNF41 (51% identical), ZNF484 (50% identical), ZNF585B (43% identical), ZNF605 (42% identical), ZNF33B (41% identical), ZNF585A (41% identical), ZNF182 (41% identical), ZNF658 (41% identical), ZNF300 (40% identical), ZNF717 (39% identical), ZNF630 (38% identical), ZNF334 (37% identical), and 164 more.
Diseases named in the same sentence as ZNF175 in open-access papers:
ZNF175 is named in the same sentence as 3 diseases in open-access papers, as found by Europe PMC text mining. Sharing a sentence is not in itself a finding about the gene and the disease. The quoted sentences say what the papers report.
placental disease (1 paper, 2024). "Differential methylation of ZNF175 may play a role in sexually dimorphic placental disease states." (PMID 39152463, 2024).
preeclampsia (1 paper, 2024). Preeclampsia is a hypertensive disorder of pregnancy that is characterized by new-onset hypertension with proteinuria presenting after 20 weeks of gestation, and depending on mild or severe forms may initially present with severe headache, visual disturbances, and hyperreflexia. "ZNF175 is hypomethylated and overexpressed in placenta of patients with preeclampsia, compared to controls." (PMID 39152463, 2024).
ZNF175 also shares sentences with these, for which no sentence is quoted: osteoporosis (1 paper).